RPS4X (ribosomal protein S4 X-linked)
Description:
Component of the small ribosomal subunit. The ribosome is a large ribonucleoprotein complex responsible for the synthesis of proteins in the cell. Part of the small subunit (SSU) processome, first precursor of the small eukaryotic ribosomal subunit. During the assembly of the SSU processome in the nucleolus, many ribosome biogenesis factors, an RNA chaperone and ribosomal proteins associate with the nascent pre-rRNA and work in concert to generate RNA folding, modifications, rearrangements and cleavage as well as targeted degradation of pre-ribosomal RNA by the RNA exosome.
Synonyms: CCG2; RPS4; SCAR; DXS306; SCR10; FLJ40595; eS4; S4
Tractability: Small molecule: an approved drug acts on it; a structure with a bound ligand is known; a high-quality ligand is known. PROTAC: UniProt records ubiquitination sites on it; ubiquitination databases record sites on it; its protein half-life has been measured; a small molecule that binds it is known. Other modalities: a drug acting on it is in phase 2 or 3 trials.
Target class: Other cytosolic protein
Gene: Protein-coding gene on chromosome X (72,255,679 to 72,277,312, reverse strand). Ensembl gene ENSG00000198034.
Subcellular location: Cytoplasm; Nucleus, nucleolus
Pathways (Reactome):
Metabolism of proteins: Eukaryotic Translation Termination; Formation of a pool of free 40S subunits; Formation of the ternary complex, and subsequently, the 43S complex; GTP hydrolysis and joining of the 60S ribosomal subunit; L13a-mediated translational silencing of Ceruloplasmin expression; PELO:HBS1L and ABCE1 dissociate a ribosome on a non-stop mRNA; Peptide chain elongation; Ribosomal scanning and start codon recognition; SRP-dependent cotranslational protein targeting to membrane; Translation initiation complex formation; ZNF598 and the Ribosome-associated Quality Trigger (RQT) complex dissociate a ribosome stalled on a no-go mRNA
Disease: SARS-CoV-1 modulates host translation machinery; SARS-CoV-2 modulates host translation machinery; Viral mRNA Translation
Metabolism of RNA: Major pathway of rRNA processing in the nucleolus and cytosol; Nonsense Mediated Decay (NMD) enhanced by the Exon Junction Complex (EJC); Nonsense Mediated Decay (NMD) independent of the Exon Junction Complex (EJC)
Cellular responses to stimuli: Response of EIF2AK4 (GCN2) to amino acid deficiency
Developmental Biology: Regulation of expression of SLITs and ROBOs
Metabolism: Selenocysteine synthesis
Gene Ontology:
Molecular function: protein binding; RNA binding; structural constituent of ribosome
Biological process: positive regulation of cell population proliferation; positive regulation of translation; ribosomal small subunit biogenesis; translation; cytoplasmic translation
Cellular component: cytoplasm; cytoplasmic ribonucleoprotein granule; cytosolic ribosome; cytosolic small ribosomal subunit; extracellular exosome; focal adhesion; membrane; ribonucleoprotein complex; ribosome; small ribosomal subunit; small-subunit processome; cytosol; nucleoplasm; nucleolus; synapse
Homologues: Orthologues: dog RPS4X (100% identical), pig RPS4X (100% identical), rat Rps4x (100% identical), rabbit RPS4X (98% identical), zebrafish rps4x (93% identical), Drosophila melanogaster RpS4 (75% identical), Caenorhabditis elegans rps-4 (63% identical). Paralogues in human: RPS4Y1 (93% identical), RPS4Y2 (92% identical).
Diseases named in the same sentence as RPS4X in open-access papers:
RPS4X is named in the same sentence as 43 diseases in open-access papers, as found by Europe PMC text mining. Sharing a sentence is not in itself a finding about the gene and the disease. The quoted sentences say what the papers report.
hepatocellular carcinoma (9 papers, 2020 to 2024). A malignant tumor that arises from hepatocytes. "The RPS4X ribosomal protein has been linked to numerous cancer types, including glioblastoma, lung adenocarcinoma, hepatocellular carcinoma, ovarian cancer, and many others." (PMID 37190091, 2023). "A study has shown that SLFN11 can act as a tumor suppressor by suppressing the mTOR pathway by targeting RPS4X in hepatocellular carcinoma, which suggests that its mutation may lead to the loss of its inhibitory effect on mTOR." (PMID 37189093, 2023). "Furthermore, SLFN11 suppresses the proliferation of hepatocellular cancer cells by interacting with the ribosomal protein S4 X-linked (RPS4X), resulting in attenuation of S6 and eIF4E phosphorylation in the ribosome complex and inhibition of the mTOR signaling pathway." (PMID 35768579, 2022). "In hepatocellular carcinoma, RPS4X is required for SLFN11 inactivation in the mTOR signaling pathway." (PMID 36474171, 2022). "Our results identified RPS4X as a protective factor against GBM, which is interesting given that it has been reported to drive the development and metastasis of hepatocellular carcinoma." (PMID 35875673, 2022). "In addition to its replication stress checkpoint functions, SLFN11 interacts with ribosomal protein S4 X-linked (RPS4X) and suppresses the mTOR signaling pathway in hepatocellular carcinoma (HCC), inhibiting HCC growth and metastasis." (PMID 35768579, 2022).
ovarian carcinoma (8 papers, 2011 to 2025). A malignant neoplasm originating from the surface ovarian epithelium. "RPS4X is associated with ovarian cancer stage and its low expression is also associated with poor survival and disease progression; however, there are still no reports on RPS4X in glioma." (PMID 36474171, 2022). "RPS4X is a ribosomal protein that has been studied as a potential prognostic marker for ovarian cancer, with low levels of the gene associated with poor survival." (PMID 35428183, 2022). "RPS4X (ribosomal protein S4 X-linked) is an oncogene described to increase cisplatin resistance and associated with poor survival and disease progression in ovarian cancer." (PMID 39513861, 2024). "We determined whether the expression of YB-1 and RPS4X were associated with survival time and disease recurrence in patients with ovarian cancer using Kaplan-Meier plots." (PMID 23800275, 2013). "We investigated whether YB-1 was associated with RPS4X and Ki67 expression in ovarian cancer." (PMID 23800275, 2013). "Several hub genes, such as RPL11, RPS4X, EIF3I, and RPS14, have been previously linked to various cancers and were confirmed to play crucial roles in ovarian cancer through this study." (PMID 39891297, 2025). "Increased levels of RPS4X have been shown to be connected to a better overall survival rate among ovarian cancer patients." (PMID 39891297, 2025). "Endogenous RPS4X was only found in the GFP-YB-1 immunoprecipitate indicating an interaction between RPS4X and YB-1 in ovarian cancer cells as well." (PMID 23800275, 2013). "RPS4X-depleted ovarian cancer cells were more resistant to cisplatin than control siRNA transfected cells." (PMID 23800275, 2013). "As platinum-based compounds are used in the treatment of ovarian cancers, we sought to correlate the levels of RPS4X in clinical samples with patient survival and disease progression." (PMID 23800275, 2013). "Altogether these results indicate that RPS4X-depleted ovarian cancer cells are resistant to apoptosis induced by cisplatin." (PMID 23800275, 2013). "In this work, we determined by immunohistochemistry the levels of both RPS4X and YB-1 in ovarian cancer samples from patients who were treated with a platinum-based chemotherapeutic regimen after their surgery." (PMID 23800275, 2013). "We next investigated the correlation between clinicopathological features of ovarian cancer cases and the expression of YB-1 and RPS4X." (PMID 23800275, 2013). "As platinum-based chemotherapy is a standard first line therapy used to treat patients with ovarian cancer, we evaluated the prognostic value of RPS4X and YB-1 at the protein level in specimen from 192 high-grade serous epithelial ovarian cancer patients." (PMID 23800275, 2013). "In addition, a depletion of RPS4X in both the OVCAR-3 and SK-OV-3 ovarian cancer cell lines induced cisplatin resistance and is consistant with our previous data on RPS4X depleted breast cancer cell lines resistant to cisplatin." (PMID 23800275, 2013). "Altogether, these results suggest that the levels of RPS4X could be a good indicator for resistance to platinum-based therapy and a prognostic marker for ovarian cancer." (PMID 23800275, 2013). "Finally, the depletion of RPS4X with different siRNAs in two different ovarian cancer cell lines reduced their proliferative growth rate but more importantly increased their resistance to cisplatin." (PMID 23800275, 2013). "One hypothesis is that depletion of RPS4X could induce a ribosomal stress which in turn leads to a slower growth rate as observed in siRPS4X transfected ovarian cancer cell lines." (PMID 23800275, 2013). "As platinum-based regimen is a major treatment for ovarian cancer, we sought to determine whether the expression of RPS4X could have prognostic significance in this cancer type." (PMID 23800275, 2013).
ovarian carcinoma (continued). "Since we recently found an interaction between RPS4X and YB-1 proteins that may affect clinical outcomes of patients, we determined the levels of expression of these proteins by immunohistochemistry in 192 clinical samples from women with ovarian cancer." (PMID 23800275, 2013). "Based on microarray studies of different cell lines, the proteins HNRPL, PABPC1, RPS4X, RPS7, and RALY are overexpressed in ovarian cancer cells resistant to oxaliplatin." (PMID 22118625, 2011).
breast carcinoma (7 papers, 2011 to 2025). "The X-linked ribosomal protein S4 (RPS4X), which is involved in cellular translation and proliferation, has previously been identified as a partner of the overexpressed multifunctional protein YB-1 in several breast cancer cells." (PMID 23800275, 2013). "The RPS4X protein was identified as a potential biomarker for controlling cisplatin resistance in breast cancer treatment." (PMID 38418940, 2024). "Our recent analyses on YB-1 in breast cancer cell lines resistant to cisplatin have indicated an interaction between RPS4X and YB-1." (PMID 23800275, 2013). "We recently found that a depletion of RPS4X increased cisplatin resistance in YB-1 overexpressing breast cancer cell lines." (PMID 22118625, 2011). "Given the growing interest in developing MCL1-targeted therapies for cancers, such as acute myeloid leukemia and breast cancer, RPS4X could represent an upstream regulatory factor worth targeting to overcome apoptotic resistance." (PMID 41154579, 2025). "The X-linked ribosomal protein S4 (RPS4X), which is involved in cellular translation and proliferation in breast cancer cell lines, has been identified as a partner of the overexpressed multifunctional protein YB-1, and RPS4X depletion leads to consistent resistance to cisplatin." (PMID 35326612, 2022). "We previously showed that RPS4X interacts with a tagged YB-1 in a breast cancer cell line." (PMID 23800275, 2013).
lung adenocarcinoma (4 papers, 2021 to 2025). A carcinoma that arises from the lung and is characterized by the presence of malignant glandular epithelial cells. "Moreover, interactions between GTF2E2 and ribosomal protein S4, X-linked (RPS4X) have been implicated in the onset of lung adenocarcinoma." (PMID 40267151, 2025). "Previous studies have associated GTF2E2 with poor prognosis in various cancers; for example, knockdown of GTF2E2 inhibits the growth and progression of lung adenocarcinoma via RPS4X in vitro and in vivo." (PMID 40267151, 2025). "Recent research reported that GTF2E2 plays an oncogenic role in lung adenocarcinoma by interacting with RPS4X." (PMID 34853466, 2022).
colorectal cancer (3 papers, 2011 to 2025). A primary or metastatic malignant neoplasm that affects the colon or rectum. "As with RPL3, deregulated RPS4X has been previously associated with various tumors and tumor phenotypes, including subgroups of colorectal carcinoma, a myelodysplasia risk signature and poor prognosis in bladder cancer." (PMID 29530001, 2018). "For instance, in colorectal cancer, RPS4X overexpression has been associated with poor prognosis and increased metastasis, suggesting that the stabilization of survival factors may contribute to tumor progression." (PMID 41154579, 2025). "For instance, RPS4X overexpression correlates with poor prognosis in colorectal cancer and intrahepatic cholangiocarcinoma." (PMID 41154579, 2025). "It is possible that HNRNPL, PABPC1, RPS4X, and RPS7 correlate with oxaliplatin resistance but are not directly involved biochemically in the process of resistance in colorectal cancer cell types." (PMID 22118625, 2011).
glioblastoma (3 papers, 2017 to 2024). The most malignant astrocytic tumor (WHO grade IV). "Although the role of RPS4X in glioblastoma has not been reported yet, it should act through the mTOR signaling pathway." (PMID 39513861, 2024).
Alzheimer disease (2 papers, 2024). A progressive, neurodegenerative disease characterized by loss of function and death of nerve cells in several areas of the brain leading to loss of cognitive function such as memory and language. "Notably, six of these proteins (RPS3A, RPS4X, RPS8, RPS14, RPS20 and RPL31) were upregulated in brain capillaries of Alzheimer’s disease patients." (PMID 38732249, 2024).
Diabetes (2 papers, 2012 to 2024). "Other health problems frequently present include congenital heart disease, hypothyroidism, diabetes, vision and hearing problems, autoimmune diseases and developmental delays.Human sex linked genes RPS4X and RPS4Y encode 2 isoforms of ribosomal protein S4." (PMID 22709827, 2012).
intrahepatic cholangiocarcinoma (2 papers, 2024 to 2025). A carcinoma that arises from the intrahepatic bile duct epithelium in any site of the intrahepatic biliary tree. "RPS4X is frequently overexpressed in various cancers, including colorectal and intrahepatic cholangiocarcinoma, and its high expression is associated with poor patient prognosis." (PMID 41154579, 2025). "A previous study suggested that overexpression of RPS4X is correlated with poor prognosis in not only colon rectal cancer but also intrahepatic cholangiocarcinoma." (PMID 39199272, 2024).
Turner syndrome (2 papers, 2022 to 2025). Turner syndrome is a chromosomal disorder associated with the complete or partial absence of an X chromosome. "Of the escape genes, SHOX, STS, KDM5C, KDM6A, UBA1, and RPS4X were associated with Turner syndrome." (PMID 36457060, 2022). "Cases of Turner syndrome, where one copy of the X chromosome is missing in females, highlight that only one copy of RPS4X is necessary for survival, although various medical and developmental problems exist." (PMID 40649992, 2025).
asthma (1 paper, 2025). "This study shows that RPS4Y1 expression is cell-specific and different to its X-linked counterpart, RPS4X, in asthma." (PMID 40649992, 2025). "RPS4X and RPS4Y1 are X and Y-chromosome-linked genes coding ribosomal subunits previously associated with inflammation, airway remodelling and asthma medication efficacy." (PMID 40649992, 2025). "Of note, RPS4X is most highly expressed in ‘basal-activated’ cells, with a similar expression level between asthma patients and healthy controls." (PMID 40649992, 2025). "We also establish that RPS4Y1 regulates a specific gene signature that is only dysregulated in males with asthma, indicating that the imbalance of RPS4Y1 and RPS4X expression between males and females may contribute to sex differences in asthma." (PMID 40649992, 2025). "The heatmaps presenting the expression of RPS4X and RPS4Y1 indicate that their expression changes with asthma in a cell-specific pattern." (PMID 40649992, 2025). "Using CRISPR-Cas9 knockout cellular models for RPS4Y1 and RPS4X, we characterised the function of RPS4Y1 in the context of the asthma-relevant processes, inflammation and fibrosis." (PMID 40649992, 2025). "Further, RPS4Y1 expression was lower in male asthma patients than in male controls, while RPS4X expression did not change in asthma for either sex." (PMID 40649992, 2025). "Finally, we confirmed in bronchial biopsies that RPS4Y1 is downregulated in asthmatic males versus males without asthma, but RPS4X demonstrated similar expression in males and females with asthma compared to healthy controls." (PMID 40649992, 2025). "However, as RPS4X expression does not change in asthma, reduced expression of RPS4Y1 has functional consequences as recognised through FEV1% predicted measurement in asthma." (PMID 40649992, 2025).
COVID-19 (1 paper, 2023). A disease caused by infection with severe acute respiratory syndrome coronavirus 2. "Although no subsequent literature has demonstrated COVID-19 vaccination-induced differential expression of RPL10, RPS3, and RPS4X in CD4+ T cells, these genes are still considered potent features." (PMID 36936955, 2023).
influenza (1 paper, 2025). An acute viral infection of the respiratory tract, occurring in isolated cases, in epidemics, or in pandemics; it is caused by serologically different strains of viruses (influenzaviruses) designated A, B, and C, has a 3-day incubation period, and usually lasts for 3 to 10 days. "For influenza, discriminatory ribosomal genes included RPL7A, RPL13, RPL18, RPL23A, RPLP2, RPS2, and RPS4X." (PMID 41020849, 2025).
mucinous adenocarcinoma (1 paper, 2023). An invasive adenocarcinoma composed of malignant glandular cells which contain intracytoplasmic mucin. "TFF3 is essential for the transcriptional regulation of these molecules, and may cooperate with RPS4X to eventually lead to the mucinous adenocarcinoma mucus phenotype." (PMID 36690709, 2023).
myelodysplastic syndrome (1 paper, 2018). A clonal hematopoietic disorder characterized by dysplasia and ineffective hematopoiesis in one or more of the hematopoietic cell lines. "The co-overexpression RPS25 and RPS4X detected in one cluster of AML has been previously identified as contributing to the poor risk signature in myelodysplastic syndrome." (PMID 29530001, 2018).
ovarian tumors (1 paper, 2013). "To summarize, all our statistical analyses indicate that high expression of RPS4X is associated with less aggressive ovarian tumors, slower disease progression, and with less deaths associated with this disease." (PMID 23800275, 2013). "To confirm the validity of the antibody against RPS4X, we performed western blot and immunofluorescence tests on control and RPS4X-depleted SK-OV-3 ovarian tumor cell lines." (PMID 23800275, 2013). "We examined the effect of depleting YB-1 protein on RPS4X levels in the ovarian tumor line OVCAR-3." (PMID 23800275, 2013). "As the immunohistochemistry study was performed on serous high-grade ovarian tumors from patients who had not received chemotherapeutic treatment, the patients showing low expression of RPS4X in their tumor tissues at surgery could correlate with an intrinsic resistance to platinum-based drugs." (PMID 23800275, 2013).
serous ovarian cancer (1 paper, 2013). "To conclude, we have established that RPS4X is a new promising prognostic marker for patients with high-grade serous ovarian cancer." (PMID 23800275, 2013). "More importantly, if RPS4X is shown to be predictive of cisplatin response either alone or in combination with other markers, this could be useful when selecting first line therapies for patients with serous ovarian cancer." (PMID 23800275, 2013).